RAC1 (Rac family small GTPase 1)
Diseases named in the same sentence as RAC1 in open-access papers (continued):
Sharing a sentence is not in itself a finding about the gene and the disease.
cancer (continued). "The migratory machinery of cancer cells is depended on interactions between specific cell cytoskeletal proteins coordinated by small GTPases, such as the Rho family of proteins (RHOA, CDC42 and RAC-1." (PMID 34321041, 2021). "Additionally, in endometrial cancers, TRPV4 regulates cancer cell invasion through RhoA/ROCK1-dependent cytoskeletal changes and in glioma cancer cells TRPV4 promotes invasion through Akt/Rac1 signaling pathway." (PMID 34356643, 2021). "Similarly, Mitogen-Activated Protein Kinase 4 (MAPK4) in 12 cancers, Serine/Threonine Kinase 32A (STK32A) and P21 (RAC1) Activated Kinase 3 (PAK3) in 10 cancers were found to be commonly downregulated." (PMID 33801837, 2021). "For this reason, a more specific path must be pursued to allow targeting of the cancer-related roles of RAC1 without affecting its physiological roles." (PMID 33397922, 2021). "Although we already know that Rac1 plays an important role in cancer, there are few clinical studies related to Rac1, and the detailed mechanism of Rac1 participating in cancer has not yet been clarified." (PMID 34079763, 2021). "Thus, the combination of Hst and Dox decreased expression of a protein that plays a role in cancer metastasis, which is MMP9 and Rac1." (PMID 32458631, 2020). "In this cluster, Rac Family Small GTPase 1 (RAC1), Caveolin 1 (CAV1), Low-density lipoprotein receptor-related protein 6 (LRP6) and collagen type I alpha 1 chain (COL1A1) were identified as proteins shown to promote EMT in various cancer." (PMID 33050615, 2020). "The expression of the Rho GTPases RAC1, RHOA, and CDC42 is also altered in several cancer types." (PMID 32526908, 2020). "While we assessed the expression of several well-known molecules implicated in cancer cell migration including P-ERK, RhoA, and Rac1, none of them were affected upon ITGB1 and SLUG knockdown in our CTC model." (PMID 32630254, 2020). "Compared to RAC1, RAC1B exhibits a number of distinctive features with respect to tissue distribution, downstream signaling and a role in disease conditions like inflammation and cancer." (PMID 33266416, 2020). "Endogenous TRAIL-R2 was shown to promote KRAS-driven cancer through cancer cell-autonomous Rac1 activation and non-cancer-cell-autonomous reprogramming of the TIME into one conducive of type 2 macrophage accumulation." (PMID 32194994, 2020). "Rac1 function specialization depending on its own compartmentalization and/or localized Rac-GEF activation may therefore be critical for the cancer cell to adapt to the harsh tumor environment in the primary tumor and metastatic sites." (PMID 32158759, 2020). "Similarly, the expression and function of DDX3 in human cancers is diversified, although DDX3 has been shown to modulate cell adhesion, motility and cancer cell metastasis via the Rac1 pathway." (PMID 32957697, 2020). "Moreover, Rac1 and Rictor suppression led to cell viability decrease in IDH1-mutated U251 cells and BTIC TS603, but not in IDH1 wild type U251 cells and BTIC GSC923, which indicates that targeting of the mTORC2/Rac1 pathway might be a potential therapeutic approach for cancers with IDH1 mutations." (PMID 32224866, 2020). "Thus, we consider that cancer cells show a metastatic phenotype as a result of CERS6 and C16 ceramide to produce a PKCζ and RAC1 complex." (PMID 32902157, 2020). "As aberrant activation of STATs is observed in most cancer types, it is not surprising to find many examples of Rac1, and other Rho-family members, influencing STAT-dependent cancer progression." (PMID 32915198, 2020).
cancer (continued). "Although Rac1/Cdc42 are recognized as attractive therapeutic targets in cancer, no selective inhibitors have advanced to human use." (PMID 31344967, 2019). "Thus, AT2R activation reduces migration, invasion, and metastasis of cancer cells by PTP1B-mediated CAV1 dephosphorylation and inhibition of the CAV1/Rab5/Rac-1 pathway." (PMID 31484460, 2019). "Thus, further studies are necessary to uncover the effect of β-catenin phosphorylation and RAC1 activation in differential KRT19/β-catenin/NUMB-mediated regulation of Notch signaling crosstalk and contiguous regulation of cancer properties." (PMID 30650643, 2019). "In cancer, CSDE1 has been shown to regulate c-Fos, c-Myc, Pten, Rac1, or Vimentin." (PMID 31027221, 2019). "In addition, the chromosomal locus containing miR-204 is frequently lost in cancers, resulting in its lower expression and resulted in BDNF/TrkB overexpression and activation of the AKT/mTOR/Rac1 signaling pathway." (PMID 31480771, 2019). "Then we speculate that HMGB1 may induce the expression of RAC1 and CDC42 followed by binding to TLR4, and activate PI3K/AKT signaling pathway, which plays an important role in cancer cell growth and malignant transformation." (PMID 30962261, 2019). "Unlike RAS proteins, which are frequently mutated in cancer (around 30%), RAC proteins (RAC1, RAC2 or RAC3) themselves are generally not found to be mutated in cancers at such a high frequency." (PMID 31027363, 2019). "The mode of action of Rac1b in cancers is not known, although one possible mode of action is that Rac1b can antagonize the activity of wild-type Rac1." (PMID 30544828, 2018). "Therefore, we examined CDC42, RAC1, and RHOA as potential target proteins of F806 based on their role in the formation and turnover of actin filaments, as well as cancer invasion and metastasis." (PMID 30327774, 2018). "Stat3 and Src/FAK/Rac1 signal are known as an vital role in controlling cell migration and invasion by regulating the expression level of genes included MMP2, 9 and it is established that the level of MMPs is positively related to cancer cell metastasis." (PMID 29423083, 2018). "Whether Rac1 can serve as a downstream target of ALK in these cancers as well, and whether and how it contributes to invasion of tumor cells in these cancers remains to be elucidated." (PMID 30558116, 2018). "Rac1 immunoreactivity was detected in the cytoplasm of carcinoma cells, while it was almost negligible in non-neoplastic mammary epithelium or stroma." (PMID 29534468, 2018). "Increased expression and activity of Rac1, a small Rho GTPase, has been shown previously in NMSC and other human cancers; suggesting that Rac1 may function as an oncogene in skin." (PMID 28277539, 2017). "Cancer cells can also acquire an invasive capacity when EMT occurs, which upregulates the level of the invasion-related protein MMP-9 and the migration-related protein RAC1." (PMID 28404892, 2017). "ITSN deficiency leading to impaired Cbl-Eps8 interaction, and enhanced mSos1-Eps8 complex formation leading to Rac1 activation, is a mechanism which has not been previously reported in cancer." (PMID 27629044, 2016). "In cancer cells, XB130 colocalizes with constitutively active Rac1 at lamellipodia." (PMID 27835612, 2016). "Among these, RAC1 and RHOA are already present in the Cancer Gene Census, adding confidence to the hypothesis that also RHOF might play a role in cancer." (PMID 26860319, 2016). "Translating the experimental observations concerning RAC1 from a neuronal system to cancer is not straightforward." (PMID 26860319, 2016). "In contrast, GLS1 does not interact with Rac1 to inhibit Rac1 activity, and consequently, cannot inhibit cancer metastasis via this pathway." (PMID 26751560, 2016). "PIAS3 SUMOylates Rac1 stabilizing the active form of the protein following HGF stimulation and therefore promoting cell migration and invasion, suggesting a possible role in cancer progression." (PMID 27104658, 2016).
cancer (continued). "Rac1 activation results in PAK1 phosphorylation, which leads to cytoskeletal remodeling, alterations in cell adhesion, as well as the EMT, all of which are required for promoting cancer cell migration." (PMID 25860930, 2015). "Another possible explanation for the incomplete attenuation of cancer cell migration by Rac1 inhibitor NSC23766 is that this inhibitor does not target the Rac-specific GEFs involved in cancer cell migration." (PMID 25888632, 2015). "Although previous studies report that CDC42 and Rac1 can activate JNK and regulate cancer cell migration, our results from current studies demonstrated that JNK could also regulate CDC42 and Rac1 expression and subsequently mediate T24 cell migration." (PMID 25402510, 2015). "SOD2, CDC42/Rac1, and JNK/c-Jun are all known to be involved in cancer development and migration." (PMID 25402510, 2015). "Despite the clear roles of Rac1 in VEGF-mediated vascular permeability, to date, whether Rac1-mediated permeability contributes to the hematogenous metastasis of cancers remains poorly understood." (PMID 25991673, 2015). "We found that DEPDC1B regulated Rac1 activities by increasing GTP loading in Rac1 did not affect Rho A activities in either normal or cancer cells." (PMID 25091805, 2014). "Although we did not investigate Rac, Cdc42, and mDia in the present study, Rac1 activity was increased in cancers of the human upper urinary tract and was related to tumor progression in our previous study." (PMID 24908363, 2014). "To analyze signaling pathways that could mediate the effects of AZA1 mediated Rac1/Cdc42 inhibition, we examined the activity of the downstream effector PAK by evaluating PAK phosphorylation in EGF-stimulated cancer cells following AZA1 treatment." (PMID 24040362, 2013). "How Armus participates in cancer has not yet been determined, yet Rab7 has an emerging role and Rac1 has a well-established function in tumor proliferation and malignancy." (PMID 23562278, 2013). "Several well-studied cancer-related genes, such as Myc, Rhoa, Lef1 and Rac1, were absent in this pathway of NMR." (PMID 24565050, 2013). "Rac1 was reported to increase the secretion and activity of MMP-2 in cancer cells." (PMID 23408967, 2013). "Our findings are in keeping with previous reports showing the importance of RhoA, Rac1 and Cdc42 in cancer progression, and also the crosstalk between these GTPases and other signaling pathways like Src-FAK in the migratory phenotype of cancer cells." (PMID 23799130, 2013). "Additionally, inhibition of Rac1/Cdc42 by AZA1 affected cytoskeletal dynamics and suppressed cancer cell migration." (PMID 24040362, 2013). "Berberine also showed anti-metastatic properties in several cancer cell lines, acting on 72 kDa type IV collagenase (MMP2), Cdc42 effector protein 1 (CDC42EP1), and ras-related C3 botulinum toxin substrate 1 (RAC1), transforming protein RhoA (RHOA) and urokinase-plasminogen activator A (PLAU)." (PMID 23213296, 2012). "Induction of integrin β4 expression dramatically increased GTP-bound Rac1, independent of stimulation from cancer cells, but did not have a significant effect on Akt phosphorylation." (PMID 22673183, 2012). "In a first attempt at understanding the signalling of RhoH in cancer cells, or rather its absence of signalling, it was shown that expression of RhoH is necessary to prevent Rac1 mediated protection from drug-induced apoptosis." (PMID 18823547, 2008). "NaV1.5 and Rac1, although they do not interact directly, exhibit significant functional connections in cancer invasion and metastasis by regulating shared signaling pathways and biological processes such as ion flow, cytoskeletal reorganization, and EMT (epithelial-mesenchymal transition)." (PMID 39673684, 2025). "Interestingly, our analysis revealed a significant negative correlation between RAC1 expression and B cell lineage infiltration scores across most cancers." (PMID 39898257, 2025).
cancer (continued). "Given that RAC1B is upregulated in various cancer types while lowly or not expressed in corresponding normal tissues, it represents a more specific target with a wider therapeutic window than total RAC1." (PMID 40548642, 2025). "Further work is needed to examine whether Lpds supports tumor-specific Rac1 signaling and whether its inhibition can reduce cancer cell migration without affecting normal cells." (PMID 41360259, 2025). "Additionally, Rac1-GTP directly engaged with signal transducers and activators of transcription 3 (STAT3) to facilitate STAT3 phosphorylation, hence enhancing the EMT of cancer cells." (PMID 41188920, 2025). "Additionally, Rac1 regulates a diverse range of cellular functions in cancer cells, including proliferation, gene expression, metabolism, and epithelial-to-mesenchymal transition (EMT), making it an attractive target for cancer therapy." (PMID 40894927, 2025). "Overall, EMT is a loosely defined mechanism of resistance to cetuximab in CRC, but inferences can be made to relate the functions of RAC1, RAC1B, and their contributions to EMT that could contribute to therapy resistance based on evidence from other cancers and CRC." (PMID 39001533, 2024). "Interestingly, though, while Rac1 appears dispensable for the regulation of inflammatory proteins after TRAIL stimulation, Rac1 was required for DR5-mediated cancer cell motility and metastasis, and similar to Fas, the MPD of DR5 was also suggested to be required to trigger this effect." (PMID 38534365, 2024). "In addition to promote Rac1 binding to FilaminA, the RhoGDI2-Rac1 axis is also involved in another signaling pathway in GC since suppressing the expression of RhoGDI2 repressed the Rac1/Pak1/LIMK1 axis, which is involved in EMT, cell migration and invasion in multiple human cancers." (PMID 36835422, 2023). "The signaling landscape that accompanies Ephexin3 in various cancer types included the tyrosine kinase receptor MET and the tyrosine phosphatase receptor PTPRF, the serine/threonine kinases MARK2 and PAK6, the Rho GTPases RHOD, RHOF and RAC1, and the cytoskeletal regulator DIAHP1." (PMID 38003617, 2023). "However, if in the future it is proposed to use azathioprine to treat VAV1-positive cancer, it would be useful to determine whether VAV1 in the tumor leads to the activation of the RAC1 pathway before treatment." (PMID 37174676, 2023). "RHO, RAC1, and CDC42 are all members of the RHO GTPase family and are involved in the regulation of cytoskeleton, cell growth, and cell cycle, which may be effective targets against malignant tumor metastasis." (PMID 37202394, 2023). "Moreover, CO-IP and confocal microscopy results revealed that the binding of Vav2 and Rac1 was enhanced in cancer cells following treatment with CCL2, which indicated that CCL2 induces the functional coupling of Vav2 and Rac1 and the formation of the Vav2-Rac1 molecular complex." (PMID 35177591, 2022). "Interestingly, GLS2 directly binds to small GTPase Rac1 independent of its glutaminase activities, which in turn inhibits Rac1 activation to suppress cancer metastasis." (PMID 33681231, 2021). "Unlike the polarization of epithelial monolayer where Rac1/Cdc42 pathway functions primarily, our data show that collective polarization of carcinoma cells is predominantly controlled by Golgi apparatus, a disruption of which results in the destruction of collective polarization over a large scale." (PMID 33499191, 2021).
cancer (continued). "As anoikis escape provides a selective advantage of cancer cells to distant dissemination and colonisation, our data suggest that interruption of the IQGAP1/Rac1/Src/FAK pathway might be effective for suppressing tumour growth and metastasis in chronically HBV-infected patients." (PMID 32632148, 2020). "Constitutive active RHOA (G14V) and RAC1 (G12V) mutants were described to have transforming properties in fibroblasts, although weakly than RAS oncogenes and for long time they were related to cancer only through their cooperative role in RAS or other oncogene-mediated transformation." (PMID 31248017, 2019). "In addition, Rac1/Mek/Erk-, Smoothened/GLI-, and NF-κB-dependent pathways have been suggested to function as effectors of the aPKC activation pathway, and different downstream effectors must also be considered to be related to the role of aPKC in cancers." (PMID 31412817, 2019). "Similarly, cancer cells also induce the EMT programme when they metastasize and invade other tissues, such that RAC1 SUMOylation could also play an important role in this context." (PMID 31578236, 2019). "While the mechanism of activation of CDC42/RAC1 by RHOG, the MAPK by RAC1, as well as the intersection with the RHOA/ROCK1/2 pathways remain topics for future work, we believe this study sheds the light on RHOG as a potentially promising target for anti-angiogenesis in cancer therapeutics." (PMID 30781697, 2019). "Among these, SUMOylated Rac1 could further induce expression of a panel of genes, including SNAI (snail family zinc finger) 1, VEGF, and N-cadherin, to facilitate EMT and metastasis of cancer cells." (PMID 29855336, 2018). "Reportedly, Rac1 contributed to LPS-mediated p38 activation in GDIα knockdown podocytes;29 and PAK1 could activate MAPK cascades in oncogenic transformation of a variety of cancer cells." (PMID 29497040, 2018). "Although, it is yet to be determined whether 1A-116 is limited to targeting the Rac1-P-Rex1 binding interface or whether it interferes with other Rac1-GEF complexes, 1A-116 represents a promising Rac1 selective inhibitor that might be of clinical relevance, particularly in cancer." (PMID 27442895, 2017). "Thus, EHop-016, through suppressing Rac1-mediated activation of PAK1, might have beneficial effects not only in cancer but also in other human diseases, including cardiovascular diseases." (PMID 27442895, 2017). "In summary, the identification of MIIP as an inhibitor of Rac1 signaling by competitive binding to its downstream effector protein PAK1 has expanded our understanding of these pathways and shed light on how the cell migration pathways can be activated in cancer." (PMID 27760566, 2016). "Together, these data confirmed that cancer cell migration in H/R-experienced cells could not be controlled by inhibition of Rac1 activity alone." (PMID 25888632, 2015). "Among them, Rac1 and ICMT were selected for further experimental validation, because Rac1 is frequently activated in tumor tissues and promotes cancer metastasis, while ICMT plays an essential role in activating Rho GTPase, including Rac1, and inhibition of ICMT leads to decrease of GTP-bound Rac1." (PMID 25361001, 2014). "No noticeable change in Rac1 activity was detected after IR exposure of the cancer cells." (PMID 25344910, 2014). "However, the structural and functional requirement for Hax-1 in Rac1-cortactin mediated signaling machinery involved in cell migration - especially with reference to cancer cell migration and metastasis - has not been fully understood." (PMID 25053987, 2014). "Conversely, in case of low or absent Rac1b expression/ activity or a low ratio of Rac1b:Rac1 expression as in Panc-1 cells, cancer cells might experience an enhanced potential for Smad3-dependent or independent migration, invasion, and possibly metastasis." (PMID 24378395, 2014).